IRF6 (interferon regulatory factor 6)
Diseases named in the same sentence as IRF6 in open-access papers (continued):
Sharing a sentence is not in itself a finding about the gene and the disease.
tumor (continued). "Since enhanced cell proliferation could be represented by the elevated MGPS (multi-gene proliferation score) and enhanced tumor size, we evaluated the association between IRF6’s TGs and both MGPS and tumor size." (PMID 36434634, 2022). "In addition, the decrease of IRF6 was related to the poor prognosis of ccRCC patients and the alterations of tumor immune cells infiltration." (PMID 34659554, 2021). "In this study, we found that IRF6 could be a tumor suppressor, which is epigenetically silenced by promoter methylation in UC." (PMID 33874979, 2021). "In addition, the decrease of IRF6 was related to the unfavorable prognosis of ccRCC patients and the alterations of tumor immune cells infiltration." (PMID 34659554, 2021). "IRF6 plays an important role in tumor genesis and inhibition." (PMID 33941190, 2021). "In addition, the expression of Ki67 was detected by IHC and was found to be significantly decreased in the Oe-IRF6 group, compared with Oe-NC, indicating that the overexpression of IRF6 inhibits the proliferation of tumor cells in tumor-bearing mice." (PMID 33941190, 2021). "Finally, re-expression of IRF6 in UC inhibited tumor growth in vitro and in an xenograft mouse model, by inducing apoptosis." (PMID 33874979, 2021). "Our results confirmed that IRF6 expression was significantly decreased in ccRCC than that in adjacent normal renal tissues, and decreased IRF6 expression was related to higher histological grade, advanced tumor stage, lymph node invasion, and distant metastasis." (PMID 34659554, 2021). "Results showed that IRF6 expression, compared with adjacent normal renal tissues, was significantly decreased in ccRCC, and decreased IRF6 expression was related to higher histological grade (G3/G4), advanced tumor stage (T3/T4), higher pathological stage (Stage III/IV) and distant metastasis." (PMID 34659554, 2021). "It was found that the tumor weight and volume decreased after the overexpression of IRF6." (PMID 33941190, 2021). "In conclusion, our results suggested that CPH may be an epigenetic modifier, modulating the expression of the potential tumor suppressor IRF6, in inhibiting tumor growth in UC." (PMID 33874979, 2021). "Nevertheless, as relatively little is currently known about the effects of BLIMP1 and KLF4 expression on normal gastric cell and GC tumor cell differentiation, the ability of IRF6 to induce lytic EBV reactivation in GC tumors may also be mediated via additional (BLIMP1/KLF4-independent) mechanisms." (PMID 40569988, 2025). "Importantly, PGM1 may reverse the inhibitory effect of IRF6 on glycolysis-mediated tumor cell proliferation." (PMID 40796729, 2025). "This evidence indicates that IRF6 may possess tumor-suppressive properties." (PMID 40796729, 2025). "In addition to its effects on epithelial cell differentiation, recent studies suggest that IRF6 may function as a tumor suppressor for various types of human epithelial cell tumors through a variety of additional mechanisms." (PMID 40569988, 2025). "Of note, forced expression of Irf6 could not rescue suppress tumor development in Ripk4-deficient, Pik3caH1047R-mutant skin, again indicating that the tumor suppressive function of Ripk4-Irf6 is dependent on Ripk4’s kinase activity." (PMID 36765696, 2023). "However, previous studies indicated that IRF6 acts as a tumor suppressor." (PMID 35012444, 2022). "It will be of considerable importance to determine whether CLP-associated IRF6 and/or GRHL3 variants also affect their tumor suppressive functions in vivo, and whether CLP/VWS patients harboring such variants might have an increased risk to develop certain types of carcinomas later in their lives." (PMID 36457487, 2022). "In addition, IRF6 is downregulated in human skin SCCs, and has a tumor suppressive function." (PMID 24216703, 2013). "IRF-6 may also act as a tumor suppressor via its interaction with maspin, a tumor suppressor gene." (PMID 23420765, 2013).
tumor (continued). "While canonical EMT is well-studied in cancer progression, the hEMT state—marked by co-expression of epithelial (e.g., CDH1, IRF6, JUP) and mesenchymal (LAMC2, ITGB4, TGFA) genes—has emerged as a driver that enhances cellular plasticity and tumor metastasis." (PMID 40777467, 2025). "Based on our findings, we propose that fibroblast IRF6 function is an important factor in the development of the stromal microenvironment and in sustaining the BCSC tumor niche." (PMID 39273037, 2024). "For example, IRF6 was expressed at significantly lower levels in DLBC, GBM, LGG and MESO than multiple tumours such as CESC, HNSC and LUSC." (PMID 38130025, 2024). "In BCSC xenografts, the difference in IRF6 expression shows a clear variation in the development of the stroma and its corresponding influence of survival on the BCSC cells in the tumor niche." (PMID 39273037, 2024). "IRF6 (interferon regulatory factor 6) belongs to the IRF family of transcription factors, which has been identified as a tumor suppressor in a variety of human cancers." (PMID 38023248, 2023). "While some reports point towards oncogenic functions for IRF6 and/or GRHL3, others describe them as tumor suppressors." (PMID 36457487, 2022). "We first detected the mRNA level of IRFs in PC, revealing that the level of IRF2, IRF6, IRF7, IRF8 and IRF9 were elevated in tumor tissues in PC." (PMID 35012444, 2022). "All our results strongly suggest that IRF6 and GRHL3 act as tumor suppressors in at least the cancer tissues we analyzed." (PMID 36457487, 2022). "We found that the level of IRF2, IRF6, IRF7, IRF8 and IRF9 were upregulated in tumor tissues in PC (P < 0.05)." (PMID 35012444, 2022). "The interferon regulatory factor 6 (IRF6) gene is a member of the IRF family of transcription factors that plays a major role in innate immune responses and is involved in tumor suppression, cell cycle regulation, and apoptosis." (PMID 36553659, 2022). "Despite this discovery, the roles of IRF6 and GRHL3 in cancers remain controversial as both factors have been described as oncogenes and tumor suppressors." (PMID 36457487, 2022). "Down-regulation of IRF6 expression can inhibit the differentiation of primary human keratinocytes in vivo and in vitro and promote the formation of RAS-induced tumor." (PMID 33941190, 2021). "Several of those genes are known tumor suppressors that are hypermethylated in solid cancers (CACNA1G, IRF6, ITGA9, and PPP2R2C) and used as biomarkers related to adverse outcome." (PMID 30285865, 2018). "Of note, IRF6 is suggested to regulate epithelial cell differentiation, and several IRF family members are known to harbor tumor suppressive functions." (PMID 21878096, 2011). "The IRF6 expression in stromal fibroblasts of tumor tissues was not restricted to the nuclei as observed in the BCSC Fi of 2D models, but was also present in the cytoplasm in 3D xenograft tissues and were mostly found along the periphery of the tumor." (PMID 39273037, 2024). "The upregulated IRF6 gene expression influenced by the BCSCs in surrounding stromal fibroblasts was found to participate in tumor fibrosis by regulating fibroblast elongation, cellular aggregation and ECM remodeling at the tumor periphery in 2D co-cultures." (PMID 39273037, 2024). "These evidences illustrate that IRF1, IRF4, IRF5, IRF6, and IRF8 may be candidate tumor-suppressors in CRC." (PMID 39384770, 2024). "As a result, the most significant positive correlations were observed between MCM4 (TG of IRF6) with both MGPS (correlation = 0.47, P = 6.7E−14) and tumor size (correlation = 0.25, P = 0.04), emphasized the important role of MCM4 in IRF6-mediated cell proliferation." (PMID 36434634, 2022). "Therefore, we suggested that the level of IRF3, IRF6, IRF7, IRF8 and IRF9 were upregulated in tumor tissues of PC." (PMID 35012444, 2022). "Some studies identified IRF6 and GRHL3 as oncogenes, while others could attribute tumor suppressive functions to them." (PMID 36457487, 2022).
tumor (continued). "The expression of IRF6 and KIF20A in tumor tissues was detected by RT-QPCR and western blot." (PMID 33941190, 2021). "Moreover, the relationship between IRF6 expression and tumor immune cells infiltration has not been elucidated." (PMID 34659554, 2021). "The mechanisms through which IRF6 and GRHL3 inhibit tumor development is not entirely elucidated yet and might be highly tissue-dependent." (PMID 36457487, 2022).
cancer (35 papers, 2011 to 2026). A tumor composed of atypical neoplastic, often pleomorphic cells that invade other tissues. "The interferon regulatory factor 6 (IRF6) is functioned as a tumor suppressor gene in several cancers and is associated with risk of CRC." (PMID 35443865, 2022). "Loss of IRF6 and IL-1β function during cervical neoplastic stages reflects a prognostic read out towards cancer development." (PMID 30089163, 2018). "Alterations in both ELF3 and IRF6 were significantly enriched in luminal A (typically ER-positive) cancers." (PMID 40790295, 2025). "The silencing of interferon regulatory factor 6 (Irf6) in cancer cells by EMT-transcription factors (EMT-TFs) ZEB1 and SNAIL minimize the pro-apoptotic effects of tumor necrosis factor (TNF) α." (PMID 38817612, 2024). "A combination of data extracted from the HPA with our own IHC analysis on representative normal/cancer tissues supported our finding of reduced IRF6 levels in cancer tissues compared to controls." (PMID 36457487, 2022). "Both IRF6 and GRHL3 have been found to be implicated in regulating EMT during development as well as in cancer progression." (PMID 36457487, 2022). "IRF-6 has a similar structure to IRF5, and its association with cancer has been rarely reported so far." (PMID 35443865, 2022). "The role of IRF6 in impairing EMT in cancer cells contradicts what is known about its physiological function." (PMID 36457487, 2022). "We were further able to confirm cancer cell-specific IRF6 protein downregulation by immunoblotting and IF staining in all those cancer types we had normal control cells available (i.e., lung, breast, skin, and oral cavity)." (PMID 36457487, 2022). "Our data showed that IRF6 along with E-cadherin was low expressed in CRC tissues compared with normal tissue adjacent to the carcinoma." (PMID 35443865, 2022). "We also identified a number of ‘cancer genes'18 as significantly mutated in PDA, including BCLAF1 (5% of cases), IRF6 (4% of cases), FLG (10% of cases), AXIN1 (5% of cases), GLI3 (6% of cases) and PIK3CA (4% of cases)." (PMID 25855536, 2015). "IRF6 is primarily associated with human craniofacial anomalies, but its association with cancer has not been reported." (PMID 38493179, 2024). "Notably, PTPN1, TRIM46, TRIM17, FCGR1A, IRF5, IRF6, and CAMK2B had a higher frequency of gain mutations in most human cancer types." (PMID 37941546, 2023). "It seems that IRF6 plays a pro-cancer role and is a promising therapeutic target in PC." (PMID 35012444, 2022). "ABCB1 gene polymorphism and ABCG2 upregulation may be responsible for the resistance of NPC cancer stem cells to chemotherapeutic drugs; tumour suppressor gene IRF6 kills cancer stem cells in NPC by targeting the ABCG2 gene." (PMID 32595725, 2020). "Finally, we discovered eight genes (MME, SOX17, AGTR1, PGR, ESR1, PAX8, C3 and IRF6) with high amplification frequency compared to other genes across the cancer types." (PMID 31879572, 2019). "Since TGFA, IRF6, and p63 are known to be involved in cancer, and in the view of our recent findings that cleft lip and palate families report more cancer, these gene-gene interactions might not only explain susceptibility to oral clefts, but also cancer." (PMID 23029012, 2012). "Therefore, it can be speculated that IRF6 and GRHL3 are genetic risk factors associated with the comorbidity of cancer and CLP." (PMID 36457487, 2022). "Therefore, we speculated that the mechanism of IRF6 downregulation and anti-cancer effect might be conservative at least in these cancers." (PMID 31019894, 2019). "These genes include SERTAD4, IRF6, TRAF3IP3, and UTP25, which are involved in embryo development, cancer, innate immune response, and epigenetic processes." (PMID 40007031, 2025). "While Program-1 was enriched with genes from a pan-cancer EMT program, it also notably included epithelial differentiation genes such as CDH1, IRF6, JUP, KLF6, and TJP2." (PMID 40777467, 2025).
cancer (continued). "We observed a consistent and significant downregulation of both IRF6 and GRHL3 in all the cancer cell lines analyzed compared to controls." (PMID 36457487, 2022). "Based on our findings, IRF6 and GRHL3 can be considered as tumor suppressor genes in various carcinomas, which makes them potential common etiological factors for cancer and CLP in a fraction of CLP-affected patients." (PMID 36457487, 2022). "The fact that the role of IRF6 and GRHL3 in cancer remains controversial makes this question even more challenging." (PMID 36457487, 2022). "Collectively, our functional assays indicate that rescue of IRF6 and GRHL3 in cancer cell lines has the potential to normalize parts of their tumorigenic phenotype by affecting proliferation, EMT, migration, and differentiation in a tissue-specific manner." (PMID 36457487, 2022). "To gain a better overview of published results on IRF6 and GRHL3 expression and function in cancer, we performed a literature search." (PMID 36457487, 2022). "Our results on reduced proliferation rate in the presence of increased levels of IRF6 and GRHL3 have been described before in cancer cell lines." (PMID 36457487, 2022). "IRF6 expression was lower in CRC tissues and liver metastasis from CRC than that in normal para-carcinoma tissue indicated by the results of immunofluorescence staining." (PMID 35443865, 2022). "Trying to solve this apparent conundrum, we herein aimed to characterize IRF6 and GRHL3 function in various types of carcinomas." (PMID 36457487, 2022). "IRF6 expression was found lower in CRC tissues and liver metastases from CRC compared with normal tissue adjacent to the carcinoma indicated by results of immunofluorescence staining." (PMID 35443865, 2022). "The protein expressions of IRF6 in human CRC tissues, normal para-carcinoma tissue and liver metastases from CRC were measured." (PMID 35443865, 2022). "As ZEB1 was a master regulator of EMT process in many cancer types, we firstly considered to analyze the expression correlation of ZEB1 and IRF6 in GC." (PMID 31019894, 2019). "CLDN3 and PSRR8 have been proven to have carcinogenic effects in OC, whereas IRF6 has not been reported in cancer." (PMID 38493179, 2024). "Finally, 379 cancer samples from TCGA and UCSC were used to extract 76 necroptosis-related genes, including NLRP3, TLR4, and IRF6." (PMID 38750159, 2024). "However, the discrepancy concerning IRF6 and GRHL3 expression and function in carcinomas is mainly derived from studies analyzing their roles in adenocarcinomas." (PMID 36457487, 2022). "Our data uncovered consistent downregulation of IRF6 and GRHL3 in all types of carcinomas analyzed." (PMID 36457487, 2022). "In the current study, we aimed to clarify the role of IRF6 and GRHL3 in various human carcinomas." (PMID 36457487, 2022). "Fittingly, IRF6 and GRHL3 are frequently found dysregulated in carcinomas." (PMID 36457487, 2022). "Furthermore, we analyzed the expression of IRF6 in two microarray gene profiling data (GSE54129 and GSE79973) that contained expression data of both normal tissues and cancer tissues." (PMID 31019894, 2019). "Furthermore, we investigated and analyzed the expression of ELF3 and IRF6 in GC tissues from TCGA by using the bioinformatics tool GEPIA, a web server for cancer and normal gene expression profiling and interactive analyses." (PMID 31019894, 2019). "Exogenous Irf6 significantly increased apoptosis of MCF-ErbB2 cells in 3D culture and noticeably reduced their clonogenicity without adhesion to the ECM in soft agar (the ability to grow in agar is a well-known consequence of cancer cell anoikis resistance)." (PMID 30545388, 2018). "However, the expression of IRF6 in ccRCC and its relationship with cancer prognosis have not been reported." (PMID 33941190, 2021). "Although the role of IRF6 and GRHL3 in carcinomas is not fully elucidated yet, it is plausible to link their expression to the differentiation status of carcinomas." (PMID 36457487, 2022).
infection (13 papers, 2011 to 2023). The state of being infected such as from the introduction of a foreign agent such as serum, vaccine, antigenic substance or organism. "A further three non-infection associated genes (CYGB, IRF6 and elastin microfibril interfacer 2 (EMILIN2)) were assessed." (PMID 37276213, 2023). "The IRF6 in blunt snout bream was highly expressed in liver, intestine and gills, and increased in the intestine, liver, spleen, kidney and gills after infection with A. hydrophila." (PMID 36503433, 2022). "Some interferon regulatory factors (irf1, irf3, irf4b, irf5, irf6, irf8) continued to show upregulation during the later stages of infection (day 6 to day 10) in virus-infected fish spleens." (PMID 36016951, 2022). "The expression of some ISGs like OAS1/2/3 and the upstream regulator of the IFNs pathway IRF6, were unresponsive in patients with severe infection." (PMID 33679778, 2021). "Irf1, Irf7, Irf8, and Irf9 transcripts were significantly induced by infection in Ifnar1-/- mice, whereas Irf6 transcripts (abundant in uninfected mice) were significantly down-regulated." (PMID 34591933, 2021). "We further found that a published derivative of MCF10A cells, MCF-MekDD, which we generated by infection of MCF10A cells with a retrovirus encoding an activated mutant of Mek (an Erk activator), displays significantly lower Irf6 levels than the parental MCF10A cells in 3D culture." (PMID 30545388, 2018). "In mandarin fish, IRF6 had a higher expression level in intestine, and significant increase was observed in skin and intestine at 6 h following the stimulation of poly(I:C), and had an increase at a later stage of infection from 120 hpi in spleen and head-kidney." (PMID 36503433, 2022). "While IL-6, IRF4, IRF6, and CXCL2 were significantly unchanged, TNF-α was significantly elevated in the infection-derived EVs at both 48 h and 72 h when compared to the control-derived EVs (* p = 0.01 and * p = 0.02, respectively) (respectively)." (PMID 36979955, 2023). "The results also suggested that IRF3 could be activated to a greater extent after poly(I:C) stimulation and SCRV infection in host cell than after the administration of IRF2 and IRF6." (PMID 29755465, 2018). "Furthermore, interferon regulatory factor 6 (IRF6) was downregulated at 2 dpi, but upregulated in human macrophages following infection." (PMID 28680683, 2017).
lip (5 papers, 2012 to 2026). "VDWS is primarily caused by nonsense or missense mutations in exons 3, 4, 7, 8, and 9 of the IRF6 gene, and is characterized by cleft lip and/or palate, language delay, dental agenesia, and labial/oral pits." (PMID 40149423, 2025). "Mutation in interferon regulatory factor 6 (IRF6) is known to cause syndromic and non-syndromic cleft lip/palate in human." (PMID 26240017, 2015). "Although the exact function of this gene remains unknown, polymorphisms in IRF6 may account for ∼12% of all cleft cases in the background of other genes, with an association of a particular V274I allele with isolated cleft lip/palate among Filipinos." (PMID 23029012, 2012). "Immunohistochemistry (IHC) for MYH3, IRF6, and GREM1 proteins and chromogenic in situ hybridization (CISH) for IRF6 and GREM1 genes were used to analyze postnatal unilateral right cleft lip tissue (ten patients) and control tissue (six patients)." (PMID 42196143, 2026).
cardiovascular diseases (2 papers, 2019 to 2021). "The IRF6 gene encodes a member of the IRF family of transcription factors which play roles in cardiovascular diseases." (PMID 31156544, 2019).